CST3 (cystatin C)
Diseases named in the same sentence as CST3 in open-access papers (continued):
Sharing a sentence is not in itself a finding about the gene and the disease.
ischemia reperfusion injury (1 paper, 2017). Adverse functional, metabolic, or structural changes in ischemic tissues resulting from the restoration of blood flow to the tissue (reperfusion), including swelling; hemorrhage; necrosis; and damage from free radicals. "In rats exposed to ischemia/reperfusion injury urinary cystatin C excretion was increased and associated with a focal decrease in proximal tubule endocytosis with no apparent change in megalin expression." (PMID 28575050, 2017).
keratoconus (1 paper, 2026). A degenerative, structural disorder of the eye, characterized by a cone-shaped protrusion of the cornea. "Cystatins (CST2, CST3, CST5), key inhibitors of cysteine proteases, were also decreased, potentially contributing to increased proteolytic activity and stromal degradation—an established pathogenic mechanism in keratoconus." (PMID 41601845, 2026).
kidney cancer (1 paper, 2023). Primary or metastatic malignant neoplasm involving the kidney. "Therefore, the causal associations on kidney cancer, between eGFR measured through creatinine and cystatin C could be so different in both clinical and genetic performance." (PMID 36069056, 2023). "This proved the fact that cystatin C might have the potential to play a role in identifying kidney function impairment for patients with kidney cancer." (PMID 36069056, 2023). "However, for eGFRcys calculated based on cystatin C,49 our results did not suggest a significant genetic causal role on kidney cancer, while the reverse MR analysis might indicate that kidney cancer was likely to decrease kidney function via the shared genetic mechanism with eGFRcys." (PMID 36069056, 2023).
Kidney Cyst (1 paper, 2017). Abnormal fluid filled sac within the kidney, either acquired or congenital. "The relationship between renal volume and cystatin C has never been studied before, but an ultrasound score of the severity of the disease (using the number of kidney cysts and renal enlargement) has not shown any correlation with serum cystatin C concentrations." (PMID 28346513, 2017).
kidney malformation (1 paper, 2023). "Serum cystatin C levels were higher in the bilateral duplex kidney malformation group than in the control group." (PMID 36103043, 2023).
laryngeal tumours (1 paper, 2004). "In matched pairs of normal mucosa and tumour tissue, statistically significant (P=0.029) decrease in tumour cystatin C concentration was found in the group of laryngeal tumours: compared to the normal tissue counterparts, the tumour cystatin C concentration decreased by a factor of 1.42." (PMID 15138478, 2004).
leptospirosis (1 paper, 2020). A contagious bacterial infection caused by spirochetes of the genus Leptospira. "Compared with HCs, leptospirosis patients had significantly higher levels of plasma (p)FL-OPN (p < 0.0001), plasma thrombin-cleaved (ptr)-OPN (p < 0.01), pFL-Gal-9 (p < 0.0001), serum creatinine (sCr) (p < 0.0001), and serum cystatin C (sCyC) (p < 0.0001)." (PMID 32610429, 2020).
lumbar disk herniation (1 paper, 2013). "Cystatin C has been described previously as a biomarker of pain in lumbar disk herniation, sciatica, and labor." (PMID 23758918, 2013).
macrosomia (1 paper, 2025). "Pregnant women in the GDM with macrosomia group had higher gestational weight gain, weight at delivery, OGTT results, glycated hemoglobin, serum triglycerides, cystatin C, apolipoprotein A1, and lipoprotein-a compared to the control group (P < 0.05)." (PMID 40797060, 2025).
malaria (1 paper, 2022). Malaria is a serious and sometimes fatal disease caused by a parasite that commonly infects a certain type of mosquito which feeds on humans. "Conversely, children with NMFI and severe AKI had higher levels of cystatin C and IL-8 compared to children with malaria-associated severe AKI." (PMID 35456111, 2022). "Furthermore, among children with malaria, a positive cystatin C test was associated with 3.59-fold increased odds of severe AKI (95% CI 2.12 to 6.09) compared to an 11.46-fold increase in the odds of severe AKI (95% CI 5.02 to 26.14) in children with a NMFI." (PMID 35456111, 2022). "The frequency of positive cystatin C was 16.7% in children with malaria compared to 26.1% in children with a NMFI (p < 0.001)." (PMID 35456111, 2022). "Cystatin C levels had moderate ability to discriminate between children with or without AKI in malaria with an area under the receiver operator characteristic curve (AUC) of 0.71 (95% CI 0.64 to 0.77) and good discriminatory ability in children with NMFI with an AUC of 0.82 (95% CI 0.72 to 0.91)." (PMID 35456111, 2022). "Children with NMFI were more likely to have a positive cystatin C test than children with severe malaria, suggesting that children with a NMFI may have a greater reduction in kidney function compared to children with severe malaria." (PMID 35456111, 2022).
male infertility (1 paper, 2025). The inability of the male to effect fertilization of an ovum after a specified period of unprotected intercourse. "And six months after surgery, the seminal cystatin C levels were significantly lower than pre-operative levels.This implied that cystatin C may ameliorate male infertility due to varicocele by modulating autophagy." (PMID 40331931, 2025).
manic episodes (1 paper, 2025). "Serum cystatin C levels were significantly elevated in BD patients, particularly those in manic episodes, compared to the healthy control group, with distinct correlation patterns with inflammatory biomarkers observed among the groups." (PMID 40256164, 2025).
meningitis (1 paper, 2024). A disorder characterized by acute inflammation of the meninges of the brain and/or spinal cord. "Salivary cystatin C concentrations were significantly higher in pigs with meningitis caused by S. suis (median = 0.76 mg/L; IQR = 0.5–1.08) compared with healthy pigs (median = 0.51 mg/L; IQR = 0.41–0.62) (p = 0.01)." (PMID 38891627, 2024).
monoclonal gammopathy (1 paper, 2021). A condition characterized by the abnormal presence of monoclonal immunoglobulins in the blood or urine. "NGAL levels may be elevated early in the asymptomatic stages of the spectrum of monoclonal gammopathy (as opposed to, e.g., cystatin C, which rises in symptomatic MM)." (PMID 34946293, 2021).
motor neuron degeneration (1 paper, 2010). "Accordingly, plasma cystatin C levels are unlikely to be directly correlated with motor neuron degeneration in ALS, though elevated levels may correlate to peripheral metabolic or inflammatory abnormalities during ALS." (PMID 21151566, 2010).
muscular dystrophy (1 paper, 2022). Muscular dystrophy (MD) refers to a group of more than 30 genetic diseases characterized by progressive weakness and degeneration of the skeletal muscles that control movement. "A potential explanation for the overestimation of kidney function when using cystatin-C based equations could be that body fat is a determinant of cystatin C and that patients with muscular dystrophy would have not only a reduction in muscle mass but also in fat mass." (PMID 34351595, 2022).
Myocardial necrosis (1 paper, 2016). Irreversible damage to heart tissue (myocardium) due to lack of oxygen after a heart attack (myocardial infarction). "Biomarkers unrelated to myocardial necrosis, such as cystatin C, copeptin, and mid-regional pro-adrenomedullin (MR-proADM), showed promise for cardiovascular risk prediction." (PMID 27219621, 2016).
nasopharyngeal carcinoma (1 paper, 2016). A carcinoma arising from the nasopharyngeal epithelium. "Cystatin C levels are associated with the prognosis of nasopharyngeal carcinoma patients." (PMID 27438568, 2016). "A high cystatin C level is an independent indicator of poor prognosis for nasopharyngeal carcinoma patients." (PMID 27438568, 2016). "We retrospectively assessed the relationship between serum cystatin C levels and nasopharyngeal carcinoma prognosis in a large cohort of nasopharyngeal carcinoma patients receiving long-term follow-up." (PMID 27438568, 2016).
neuroendocrine tumour (1 paper, 2016). "Here, CST3 was downregulated in non-neuroendocrine tumour tissue and that this downregulation correlated with increasing Gleason Grade." (PMID 27685442, 2016).
non-Hodgkin B-cell lymphoma (1 paper, 2017). "Hence, they considered cystatin C as a potential marker for relapse in patients with non-Hodgkin B-cell lymphoma." (PMID 28282874, 2017).
obstructive uropathies (1 paper, 2013). "Additionally, cystatin C and ß2-microglobulin concentrations were significantly higher in bilateral renal agenesis compared to obstructive uropathies (p = 0.005 and p<0.001, respectively)." (PMID 23717461, 2013).
osteomyelitis (1 paper, 2024). An acute or chronic inflammation of the bone and its structures due to infection with pyogenic bacteria. "Major complications occurred more often in individuals with stage IV PI, individuals without osteomyelitis, and individuals with pathological blood concentrations of cystatin c, calcium, and vitamin B12 as well as normal blood concentrations of HbA1c." (PMID 38123748, 2024). "In the Basel Decubitus Approach, the absence of osteomyelitis, pathological levels of cystatin c levels, calcium and vitamin B12 levels as well as normal HbA1c levels were associated with major complications after flap surgery." (PMID 38123748, 2024). "In the Basel Decubitus Approach, stage IV PI, absence of osteomyelitis, reduced vitamin B12 and calcium, elevated cystatin c, and normal HbA1c should be addressed to reduce major complications." (PMID 38123748, 2024).
osteosarcoma (1 paper, 2025). A usually aggressive malignant bone-forming mesenchymal neoplasm, predominantly affecting adolescents and young adults. "SPP1, VEGFA, EMMPRIN, MIF, uPAR, Angiogenin, and Cystatin C were among the most highly expressed analytes in both patient specimens and in cell line conditioned media, demonstrating that the osteosarcoma cells themselves are a cellular source of these molecules." (PMID 39896512, 2025).
pancreatic ductal adenocarcinoma (1 paper, 2025). An infiltrating adenocarcinoma that arises from the epithelial cells of the pancreas. "In pancreatic ductal adenocarcinoma, CSTB competes with cystatin C (CSTC) to bind cathepsin B (CTSB), but CSTC has stronger cathepsin inhibitory activity." (PMID 39996856, 2025).
paraplegia (1 paper, 2013). Complete paralysis of the lower half of the body including both legs, often caused by damage to the spinal cord. "In a hypothetical patient with paraplegia and untreated thyroid disease, neither cystatin C nor creatinine would be expected to allow for unbiased kidney function assessment." (PMID 23991042, 2013).
parasitemia (1 paper, 2022). "This significant increase in cystatin C was noted in absence of clinically relevant azotemia and correlated to the level of parasitemia." (PMID 36230418, 2022).
perinatal asphyxia (1 paper, 2021). A disorder caused by a lack of blood flow or gas exchange to or from the fetus in the period immediately before, during, or after the birth process. "We hereby would also like to mention that data on cystatin C values or trends in perinatal asphyxia + WBH were not retrieved in this meta-analysis, so they cannot be provided." (PMID 34200017, 2021).
Peritoneal Fibrosis (1 paper, 2019). Disorder characterized by a wide range of structural changes in PERITONEUM, resulting from fibrogenic or inflammatory processes. "In the current study, cathepsin B ameliorated the thickening of the submesothelial layer in a peritoneal fibrosis mouse model and its inhibitor, cystatin C, attenuated the effect of cathepsin B, suggesting a possible role for cathepsin B in reducing peritoneal fibrosis in patients receiving PD." (PMID 31815017, 2019). "However, the roles of cathepsin B and cystatin C in peritoneal fibrosis have not been investigated." (PMID 31815017, 2019).
peritonitis (1 paper, 2015). Inflammation of the peritoneum (tissue that lines the abdominal wall and covers most of the organs in the abdomen). "Compared to the control group and treated animals, peritonitis increased the levels of β-2 microglobulin at 3 h and 18 h and the levels of KIM-1, cystatin-C, osteopontin and VEGF-A at 18 h (P < 0.05)." (PMID 26498824, 2015).
pleural tumors (1 paper, 2021). "Like cystatin C, immunoreactive cystatin M/E levels (median concentration into the pleural space: 0.14 nM) are significantly higher in effusions of primary pleural tumors (mesotheliomas) compared to secondary pleural tumors (3.4 μg/L vs. 2.5 μg/L)." (PMID 33919854, 2021).
poisoning (1 paper, 2011). A condition or physical state produced by the ingestion, injection, inhalation of or exposure to a deleterious agent. "The aim of this study was to validate the predictive value of serial creatinine concentrations and to study the utility of cystatin C and neutrophil gelatinase-associated lipocalin (NGAL) as predictors of outcome in patients with acute paraquat poisoning." (PMID 21291964, 2011). "The rate of increase in creatinine or cystatin C over the first 24 h may be useful for predicting outcomes in patients with acute paraquat poisoning." (PMID 21291964, 2011).
Polydipsia (1 paper, 2021). Excessive thirst manifested by excessive fluid intake. "Chronic STD-Li treatment resulted in significant polyuria and polydipsia, elevated blood levels of creatinine and cystatin C, and increased levels of kidney nephrin and podocin—all suggestive of impaired renal function." (PMID 34834241, 2021).
polyneuropathy (1 paper, 2010). A disease or disorder affecting more than one nerve. "A recent study using small numbers of test subjects reported a significant reduction in CSF cystatin C concentration in ALS patients relative to individuals with polyneuropathy, as measured by ELISA." (PMID 21151566, 2010).
postherpetic neuralgia (1 paper, 2023). "For example, cystatin C levels in the cerebrospinal fluid appear to be a predictive marker for postherpetic neuralgia in patients with varicella-zoster virus and a pain marker in women experiencing labor pain." (PMID 36830917, 2023).
Primary hypothyroidism (1 paper, 2012). A type of hypothyroidism that results from a defect in the thyroid gland. "It has been shown that serum Cr and cystatin C levels are affected by serum TSH in primary hypothyroidism and in CH." (PMID 23261862, 2012).
prostatic tumors (1 paper, 2009). "We unravelled novel molecular mechanisms by which cystatin C affects tumor cell invasion demonstrating that cystatin C expression was downregulated in primary prostate tumors compared with benign tissues in 448 patients." (PMID 19956729, 2009).
rectal cancer (1 paper, 2023). A primary or metastatic malignant neoplasm that affects the rectum. "The subgroup based on tumor location showed that the creatinine/cystatin C ratio could effectively stratify the prognosis of patients with rectal cancer." (PMID 37409249, 2023). "However, the creatinine/cystatin C ratio is a useful prognostic factor in predicting OS in rectal cancer patients, but not PFS." (PMID 37409249, 2023).
Renal cyst (1 paper, 2021). A fluid filled sac in the kidney. "We have found that blood pressure correlated with serum cystatin C and renal cyst diameter in this group of patients." (PMID 34912759, 2021). "Cystatin C and renal cyst diameter were significant determinants of elevated blood pressure in our cohort." (PMID 34912759, 2021).
renal toxicity (1 paper, 2025). "In the current study, cystatin C effectively predicted acute renal toxicity (AUC = 0.993, P < 0.001)." (PMID 40361175, 2025). "Linear regression analysis was used to assess predictors of acute renal toxicity, and significant associations were found with the following variables: serum creatinine on day 1 (P = 0.000), serum creatinine on day 2 (P = 0.000), proteinuria ACR (P = 0.023), and cystatin C (P = 0.000)." (PMID 40361175, 2025).
retinoblastoma (1 paper, 2021). A malignant tumor that originates in the nuclear layer of the retina. "In our small series of children with retinoblastoma with normal kidney function, cystatin C-based carboplatin dosing using the Schwartzcys equation led to more accurate carboplatin exposure than the other cystatin C- or creatinine-based eGFR methods." (PMID 34885072, 2021).
rheumatic disorder (1 paper, 2020). Inflammatory and degenerative diseases of connective tissue structures, such as arthritis. "In the present study, corticosteroid treatment did not seem to be an interacting factor, since the patients that could potentially have been prescribed corticosteroid treatment for their rheumatic disorder did not have higher levels of cystatin C in their plasma samples." (PMID 32824680, 2020).
rheumatic fever (1 paper, 2025). A post-bacterial multisystem inflammatory disease occurring as a post-infectious, nonsuppurative sequela of untreated streptococcus pyogenes (Group A streptococcus [GAS]) pharyngitis, and mainly occurs in individuals aged 5 to 15 years. "Cystatin C–based eGFR may more accurately predict benzylpenicillin clearance, enabling precision dosing for long-acting preparations used for treatment of syphilis and prevention of rheumatic fever." (PMID 40391929, 2025).
rickets (1 paper, 2021). Bone softening and weakening usually caused by deficiency or impaired metabolism of vitamin D. Deficiency of calcium, magnesium, or phosphorus may also cause rickets. "Children with a history of rickets had a reduced glomerular filtration rate as estimated from plasma cystatin C concentration." (PMID 33675347, 2021).
schistosomiasis (1 paper, 2016). An infectious disease caused by parasitic trematodes of the genus Schistosoma that colonize human blood vessels and release eggs that can cause granulomatous reactions leading to acute (swimmer's itch or acute schistosomiasis syndrome) or chronic disease. "Their blood pressure was measured, urine examined via dipstick and albumin/creatinine ratio and blood drawn for creatinine, cystatin C and sero-markers for schistosomiasis." (PMID 27875991, 2016).
septic shock (1 paper, 2024). Shock caused by infection; frequently caused by gram negative bacteria, although some cases have been caused by other bacteria, viruses, fungi, and protozoa; characterized by fever, chills, tachycardia, tachypnea, and hypotension. "Longer RRT duration (7.0 vs. 9.6 d, p = 0.002, OR = 0.94), higher serum cystatin C levels (1.2 vs. 3.2 mg/L, p < 0.001, OR = 0.46), and the presence of septic shock (28.1% vs. 41.5%, p < 0.001, OR = 0.63) were associated with reduced likelihood of RRT weaning." (PMID 38416516, 2024).
squamous carcinoma (1 paper, 2004). "Similarly, the overproduction of active recombinant cystatin C resulted in a pronounced reduction in Matrigel invasion of murine squamous carcinoma cells." (PMID 15138478, 2004).
squamous cell carcinoma of the head and neck (1 paper, 2004). "The role of cystatin C in the invasive behavior of squamous cell carcinoma of the head and neck (SCCHN) has not been investigated so far." (PMID 15138478, 2004).
status epilepticus (1 paper, 2020). Status epilepticus is defined as a continuous seizure lasting more than 30 min, or two or more seizures without full recovery of consciousness between any of them. "During acute hippocampal injury or status epilepticus induced epileptogenesis, the Cystatin C gene and protein expression levels are increased in the hippocampus and in the DG." (PMID 32438638, 2020).
substance abuse (1 paper, 2013). The use of a drug for a reason other than which it was intended or in a manner or in quantities other than directed. "Certain data were not collected including substance abuse, mental health as well as specific biomarkers such as cholesterol, D–dimer, cystatin C and IL–6 all of which have been found to predict HIV treatment outcomes among older adults in western cohorts." (PMID 24098434, 2013).